IL18 (interleukin 18)
Diseases named in the same sentence as IL18 in open-access papers (continued):
Sharing a sentence is not in itself a finding about the gene and the disease.
kidney disease (continued). "Research has demonstrated that interleukins such as Interleukin 1 (IL-1), IL-6, and interleukin 18 (IL-18) manifest substantial expression alterations in renal tissues of DKD patients, exhibiting a close correlation with renal disease." (PMID 41368583, 2025). "Taken together, these data suggest that the proteins ASC, IL-18, uPA, EGF, NGAL, and CRP contribute significantly to the inflammatory response in renal diseases." (PMID 35355862, 2022). "Patient characteristics, including sex, age, body mass index (BMI), etiology of primary renal disease, basic monthly biochemical data, ROS, SOD3, IL-2, IL-6, and IL-18, were analyzed." (PMID 35740095, 2022). "IL-18 has been identified as a potential biomarker for renal disorders in patients with and without SARS-CoV-2 infection." (PMID 37626956, 2023). "Patients with active renal disease also have higher serum levels of IL-18 than those without renal activity." (PMID 33732720, 2021). "Collectively, our results suggested that the crosstalk between PBMCs and PT epithelial cells during HEV infection and the signals axes IFN-γ/chemokines and IFN-γ/IL-18 and KIM-1 could be the mechanisms mediated by HEV during renal disorders." (PMID 32824088, 2020). "The crosstalk between immune cells and epithelium and consequently the signal axes IFN-γ/chemokines and IFN-γ/IL-18 and KIM-1 could be the immune-mediated mechanisms driven by HEV during the renal disorders." (PMID 32824088, 2020). "Patients with active renal disease had statistically significantly higher serum IL-18 when compared to patients without active renal disease [ratio of GM 1.37; 95% CI 1.14, 1.63; p < 0.01]." (PMID 29930551, 2018). "Patients with active renal disease had statistically significantly higher serum levels of IL-18 compared to those without renal activity (p = 0.03)." (PMID 29930551, 2018). "Our study did not confirm IL18 as a useful biomarker to assess the activity of renal disease, as reported by others." (PMID 29026368, 2017). "In this study, plasma SOD3 and IL-18 levels were significantly correlated with the onset of first kidney disease-related hospitalization or death and could be applied as novel predictors in clinical practice." (PMID 35740095, 2022).
bacterial infection (64 papers, 2011 to 2025). "The secretion of IL-1β and IL-18 in human macrophages treated with β-hemolysin from S. agalactiae was associated with NLRP3 inflammasome activation during bacterial infection-mediated fetal death." (PMID 36761775, 2023). "As for NLRP-3 inflammasome, research has confirmed that NLRP-3 can be activated in the case of bacterial infection, promoting the synthesis and secretion of downstream IL-1β, IL-18, and other proinflammatory mediators, and then causing extensive tissue damage." (PMID 36157218, 2022). "Furthermore, in animal models, IL-18-deficient mice were more susceptible to bacterial infections than normal ones and showed uncontrolled disease progression." (PMID 35626130, 2022). "In combination with our study, the KEGG enrichment analysis results indicated that bacterial infection is associated with CH, and the relatively low expression level of IL-18 in CH may increase the vulnerability of children with CH to infections by pathogens such as bacteria." (PMID 41169358, 2025). "Notably, viral and bacterial infections differ in their immune profiles, with viral infections typically associated with increased IL-15 and natural killer cell activity, and bacterial infections with elevated IL-18." (PMID 40565346, 2025). "Low expression of NLRP1 and NLRP12 might be related to a risk of susceptibility for bacterial diseases, via reduced cleavage of pro-IL-1β and pro-IL-18 to produce mature isoforms, and via avoidance of infected macrophage lysis which contributes to pathology in TB." (PMID 31821366, 2019). "The process that leads to the secretion of inflammatory cytokines interleukin 1β (IL-1β) and interleukin 18 (IL-18) is one of the mechanisms of response to external agents, such as bacterial infections, where NETosis is also involved." (PMID 40283181, 2025). "The destruction of SSMs is a common feature associated with inflammation and viral or bacterial infection, while QS-21 has been verified to activate ASC-NLRP3 inflammasome and subsequent IL-1β/IL-18 release." (PMID 38750307, 2024). "Pyroptosis is an inflammatory programmed cell death pathway that responds to intracellular bacterial infections with unique characteristics: cells rupture and release pro-inflammatory cytokines such as IL-1β and IL-18." (PMID 39042701, 2024). "In animal models of bacterial infections and traumatic stress, IL-18-mediated inflammation has mostly been explored." (PMID 37296436, 2023). "In these experiments, we noticed that IL‐18 levels appeared to be increased at the condition of high MOI of bacterial infection." (PMID 37575012, 2023). "NLRP3 inflammasome activation is a highly regulated process for controlling the secretion of potent inflammatory cytokines, such as IL-1β and IL-18, which are essential during bacterial infection and the inflammatory response." (PMID 38001788, 2023). "We found that IL-18 negatively regulated the severity of the skin inflammation induced by the bacterial infection, whereas IL-1β was involved in controlling the bacterial burden." (PMID 37910490, 2023). "We found that IL-18 negatively regulated the exacerbation of skin inflammation induced by the bacterial infection, whereas IL-1β was involved in the control of the bacterial burden." (PMID 37910490, 2023). "The level of IL-18 increases during systemic bacterial infection or under stress conditions, which can enhance IFN-γ production." (PMID 35874724, 2022). "NKB cells expanded rapidly within 24 h and activate innate lymphocytes to protect against microbial infection via secretion of interleukin (IL)-18 and IL-12 in response to bacterial infection." (PMID 33679805, 2021). "Increased expression in the Nlrp3 (Cryopyrin) gene suggests that the MCs can have a stronger ability to release pro-inflammatory cytokines such as IL-1β and IL-18 in response to bacterial infection and other insults." (PMID 33479210, 2021).
bacterial infection (continued). "Compared with the LPS group, genes including Maf, IL-18, H2-Ab1, H2-DMa, H2-Eb1, Gsdmd, Ahsg, Alb, and Gc enriching in ‘Intestinal bowel disease’ and bacterial infection were enhanced in the Ct + LPS group." (PMID 34917080, 2021). "In response to viral and bacterial infection these inflammasomes trigger caspase-1 activation and subsequently induce the release of mature pro-inflammatory interleukins such as IL-18, contributing to the immune response to pathogens." (PMID 32155831, 2020). "It has been reported that the mRNA abundance of IL-18 by porcine immune cells is increased during bacterial infections to increase resistance." (PMID 32844150, 2020). "The secretion of IL-18 by endothelial cells, mononuclear macrophages, and epithelial cells is increased during bacterial infection, which promotes IFN-γ release from the T lymphocytes or NK cells." (PMID 32851082, 2020). "The activation of the NF-κB pathway promotes the assembly of the NLRP3 inflammasome and the secretion of IL-1β and IL-18 to intracellular bacterial infection." (PMID 33414782, 2020). "We found that the Fas-mediated pathway for IL-18 release was important for host defense against bacterial infection." (PMID 30717382, 2019). "However, because IL-18 is also produced from macrophages by LPS stimulation and is also an activator of MyD88 signaling, it may also influence the development of disease associated with bacterial infection." (PMID 31507610, 2019). "Oral infection of mice showed that abnormal expression of hemolysin in vivo alerts the immune system and induces caspase-11-dependent enterocyte pyroptosis and IL-18 secretion, which significantly constrains bacterial infection in the gut." (PMID 30138458, 2018). "Both IL-1β and IL-18 cytokines were expressed intracellularly during bacterial infection, but only the former was released and detected in the extracellular environment." (PMID 28469996, 2017). "The IL-23 / IL-22 / IL-18 axis is essentially involved in host defence and in mediating and regulating inflammatory immune responses upon parasitic and bacterial infection." (PMID 27322540, 2016). "Attempts at panel tests, including CRP combined with IL-18 because of its role in anti-viral immunity, have been unsuccessful in differentiating viral from bacterial infection." (PMID 26672961, 2015). "IL-18 is a known inducer of IFN-γ during bacterial infection, and results presented here demonstrate that these two cytokines are concurrently up-regulated within the first 6 h of A. pleuropneumoniae infection." (PMID 26018580, 2015). "LM has been previously shown to stimulate IFN-γ production by memory CD8 T cells that are not specific for LM antigens but respond due to their sensitivity to IL-12 and IL-18 induced by the bacterial infection." (PMID 21980291, 2011). "Furthermore, lymphatic sinus-lining macrophages produce IL-18 in response to bacterial infection, stimulating innate lymphocytes to produce IFNγ, which enhanced macrophage antibacterial function." (PMID 39890933, 2025). "For instance, caspase-12 was shown to inhibit mucosal immunity to bacterial infection via suppression of the Nod-Rip2-NF-kB signaling pathway, as well as via inhibition of caspase-1 activation and subsequent IL-1β and IL-18 secretion, although the latter remains controversial." (PMID 41012634, 2025). "Our results identify a BTN/TCR-independent but IL-18 and inflammasome-dependent activation pathway of Vδ2 T cells, which might be relevant for the role of Vδ2 T cells during bacterial infections." (PMID 41306552, 2025). "IL-18 has also been shown to induce IL-22 during intestinal bacterial infection." (PMID 35874724, 2022). "BMMs that are mobilized in response to bacterial infections within peripheral tissues are known to be potent inducers of pro‐inflammatory interferons (eg, IFNγ), as well as additional cytokines and chemokines such as IL‐1, IL‐18, Ccl3, Cxcl9, and others." (PMID 32841534, 2020).
bacterial infection (continued). "Additionally, caspase-8 may also activate GSDMD and promote the maturation of IL1β and IL18, as observed in the context of bacterial infections." (PMID 41173854, 2025). "IL-1β, IL-6, IL-18, and tumor necrosis factor (TNF)-α are pro inflammatory cytokines, and procalcitonin (PCT) and C-reactive protein (CRP) are nonspecific markers of systemic inflammation that increase sharply during pathogenic infections including bacterial infections." (PMID 40532039, 2025). "Even though (a) IL-1β/IL-18 secretion might occur independently of pyroptosis and (b) caspase-1 or caspase-11 deletion is more severe than IL-1β/IL-18 ablation in some bacterial infections, usually cytokine release and cell death are overlapping events necessary for optimal host defense." (PMID 30459758, 2018). "IL-18-deficient mice nasally infected with S. flexneri developed more severe inflammation in the lungs compared with wild type mice, because they could not eliminate the bacterial infection." (PMID 30717382, 2019). "Here, we show that two key mediators, IL-18 and TL1A are essential for initiating alternative Th1 cell stimulation and that this pathway is essential for rapid clearance of three important bacterial infections." (PMID 28817719, 2017). "Apart from IFN-γ, IL-4 and IL-10, there are several cytokines, such as IL-12, IL-2, IL-1, IL-18 and TNF-α that are involved in the regulation of immune responses to bacterial infections." (PMID 26619346, 2015). "shinshuense, and found that mycolactone inhibited IL-1β secretion, but not IL-18, resulting in the exclusive induction of IL-18 by the bacterial infection." (PMID 37910490, 2023). "The participation of NAIP in non-bacterial infection was also demonstrated in HIV-1-infected human monocyte-derived macrophages, in which hNAIP was activated by HIV-1 glycoprotein 41 (gp41) leading to the NLRC4 recruitment and IL-18 secretion." (PMID 38124741, 2023). "During bacterial infection, bacterial proteins in the cytoplasm are detected by NAIPs to activate the NLRC4 inflammasome, which results in the processing and activation of precursors of IL-1β and IL-18 cytokines for extracellular secretion." (PMID 36833425, 2023). "To determine whether bacterial infection influences circulating immune cells from the bone marrow in response to MCP-1 and IL-18, a MCP-1 controller, we intraperitoneally (ip)." (PMID 34073235, 2021). "In any case, the susceptibility of GSDMD and other GSDM deficient mouse strains to infectious agents and its comparison to mice lacking caspase-1, caspase-11, IL-1β, and/or IL-18 remains to be established, especially in non-bacterial infection contexts." (PMID 30459758, 2018). "Although IFNγ production may be maintained in ESRD patients through IL-12/IL-18 stimulation of MAIT cells, the lower levels of TNFα production in response to microbial stimulation point to defects in the response to bacterial infection." (PMID 29868028, 2018). "Indeed, similar to natural killer (NK) cells, MAIT cells have been shown to be activated by cytokines such as IL-12 and IL-18 produced by innate immune cells during bacterial infections, even in the absence of TCR ligation." (PMID 35979352, 2022). "These independent studies suggest that pyroptosis might lead to extrusion of infected enterocytes and promote bacterial infection in vivo even in the absence of IL-1α, IL-1β, and IL-18." (PMID 30138458, 2018). "Flagella from Salmonella, Yersinia, and Pseudomonas activate the NLRC4 inflammasome in splenic CD8α+ DCs to release IL-1β and IL-18; IL-18 can stimulate IFN-γ production from non-cognate memory CD8+ T cells in the spleen thereby enhancing host resistance to bacterial infection." (PMID 24409181, 2013). "Considering that IFNγ is known to play a protective role during several bacterial infections, including B. pseudomallei, these results suggested that the reduced resistance of Il-18-/- mice to B. pseudomallei infection may be due to lack of IFNγ induction." (PMID 22241982, 2011).
inflammation (63 papers, 2009 to 2026). Aberrant reaction of the microcirculation characterized by movement of fluid and leukocytes from the blood into extravascular tissues. "As a member of the IL-1 family of cytokines, IL-18, a prominent cytokine associated with acute lung inflammation, is steadfast following LPS injury (p = 0.0021) and diminished in the face of LPS injury followed by CDCs (p = ns)." (PMID 41592104, 2026). "Elevated IL-1β and IL-18 production by NLRP3 inflammasome-mediated pyroptosis of human primary trophoblasts has been implicated in the induction of placental inflammation and PE syndrome." (PMID 36829486, 2023). "In COVID‐19 patients, the activation of inflammasomes in lung macrophages leads to the release of IL‐1 and IL‐18, which may cause excessive lung inflammation." (PMID 40211890, 2025). "In addition, other pro-inflammatory cytokines such as IL-1α, IL-12 and IL-18 are linked to pancreatic islet inflammation." (PMID 32126084, 2020). "In a conventional allergen challenge model with ragweed extract, IL-18 administered at sensitization increased eosinophilic lung inflammation but had the opposite effect if given during late challenges." (PMID 40777291, 2025). "Interleukin 18 (IL-18) is a pro-inflammatory cytokine released by tubular cells due to renal inflammation." (PMID 41353114, 2025). "Elevated expression and urinary levels of IL-18 in obese individuals contribute to chronic inflammation and renal damage." (PMID 40703753, 2025). "Previous studies have suggested a significant role of pro-inflammatory cytokines, such as IL-1β and IL-18, in liver inflammation and damage." (PMID 40379874, 2025). "Studies suggest that in HI and WMI models, microglia trigger severe brain inflammation via caspase-1-dependent pyroptosis, releasing IL-1β and IL-18, which impair OPC differentiation and maturation." (PMID 40254577, 2025). "The TLR4/NLRP3 pathway is critical in the pathogenesis of ALI, causing sustained production of cellular factors such as IL‐1β and IL‐18, which ultimately leads to a massive outbreak of lung inflammation, resulting in tissue injury and even ARDS." (PMID 39139945, 2024). "NLRP3 inflammasomes are critical in ISO-induced cardiac inflammation as they promote the cleavage and activation of IL-18, resulting in the initiation of cardiac inflammation." (PMID 37298222, 2023). "It is likely that patients with an advanced disease process and chronic inflammation have reduced IL-18 expression in gingival tissue due to the influence of other pro-inflammatory mediators." (PMID 36289627, 2022). "Consistent, treatment of silica-instilled mice with tetracycline significantly reduced pulmonary caspase-1 activation as well as IL-1β and IL-18 production, thereby ameliorating pulmonary inflammation and lung injury." (PMID 35130879, 2022). "The mitogen-activated protein kinase 2 (MAP3K2) is necessary for the IL-18-Th1 mediated intestinal inflammation via the IL-18-MAP3K2-JNK axis." (PMID 36032110, 2022). "Therapeutic neutralization of IL-18 also diminished genital inflammation, indicating an important role for this cytokine in promoting neutrophil-dependent immunopathology." (PMID 34047696, 2021). "Our previous study has demonstrated that PM2.5 induces lung inflammation, represented as increased levels of TP, IL-1β, IL-18, and cell number in the BALFs of BALB/c mice." (PMID 30992001, 2019). "It was reported that IL-18 expression in synovial tissue correlates with the severity of joint inflammation and the levels of pro-inflammatory cytokines tumor necrosis factor alpha (TNFα) and IL-1β." (PMID 31861496, 2019). "Interleukin (IL)-18 expression in synovial tissue correlates with the severity of joint inflammation and the levels of pro-inflammatory cytokines." (PMID 31861496, 2019).